ATM (ATM serine/threonine kinase)
Diseases named in the same sentence as ATM in open-access papers (continued):
Sharing a sentence is not in itself a finding about the gene and the disease.
cancer (1,768 papers, 1997 to 2026). A tumor composed of atypical neoplastic, often pleomorphic cells that invade other tissues. "Epigenetic silencing of ATM has been associated with cancers such as lung, breast, colorectal, and head and neck squamous cell carcinomas." (PMID 41557625, 2026). "This suggests potential synthetic lethal interactions between Topoisomerase-II and ATM kinase, offering a therapeutic strategy to target ATM-deficient cancers." (PMID 41557625, 2026). "Germline WES identified a splice-altering pathogenic variant in ATM (c.2250G>A, p.Lys750=), confirming hereditary cancer predisposition." (PMID 41889691, 2026). "Resistance arises when cancer cells develop efficient DNA damage repair mechanisms by activating regulators of DNA damage response, including ataxia-telangiectasia mutated (ATM) and ataxia-telangiectasia and Rad3-related (ATR) proteins." (PMID 41335461, 2025). "While individuals with heterozygous ATM mutations do not have AT, it is reported as a cancer predisposition factor, as ATM gene orchestrates double-strand break signaling (DBSs) and replication-stress responses, a hallmark of cancer." (PMID 41378284, 2025). "Lastly, while olaparib is not FDA‐approved for ATM‐mutated NSCLC, we initiated treatment based on preclinical evidence and extrapolation from other ATM‐mutated cancers." (PMID 40622001, 2025). "The efforts culminated in the identification of a compound endowed with striking ATR inhibitory activity and remarkable cell growth inhibitory effects against ATM-deficient cancer lines." (PMID 40256842, 2025). "Other studies suggest that ATM deficiency impairs DNA damage response mechanisms but also increases cell susceptibility to apoptosis, which is especially evident in cancer cells." (PMID 40860911, 2025). "Among other cancer susceptibility genes, associations were seen for ATM (p = 0.0013), BRCA1 (p = 0.0015), BARD1 (p = 0.00021), CHEK2 (p = 0.039), RAD51D (p = 0.0065), MSH3 (p = 0.0025)." (PMID 39749474, 2025). "In this group, the most frequently mutated gene was ATM, whose mutations predispose to an increased risk of many cancers, and in the case of PDAC, this frequency is even three times higher." (PMID 41155399, 2025). "The sample with the highest mutational burden (TC627) carried an ATM cancer variant, a component of the DSBR pathway." (PMID 41353477, 2025). "ATM signalling also supports the differentiation of myofibroblastic cancer-associated fibroblasts, which are known to inhibit T-cell infiltration and antitumor immunity." (PMID 40256842, 2025). "Approximately 1–2% of Caucasian adults in the U.S. carry a pathogenic ATM heterozygous variant, which is associated with increased risks of breast, pancreatic, prostate, and possibly other cancers." (PMID 41331641, 2025). "We next wanted to extend our findings from HeLa cells into cancer cell lines bearing pathogenic BRCA1 or ATM mutations." (PMID 39994444, 2025). "Of the 18 patients with mutations in the BRCA1 and BRCA2 genes, 14 had a family history (FH) of cancer; of the 7 patients with mutations in the ATM gene, 5 had a cancer FH, and of the 34 patients with other altered genes, 27 had a cancer FH." (PMID 40259910, 2025). "In contrast, cancer cells with partial ATM loss or A-T cells under high dose irradiation of 5 Gy often over-express the miRNA-181 family to further weaken the immune context." (PMID 41065894, 2025). "Loss of SETD1A from both BRCA1-deficient and ATM-deficient cancer cells was associated with resistance to Olaparib, explained by partial restoration of homologous recombination." (PMID 39994444, 2025). "Of known cancer susceptibility genes, some evidence of association was seen for ATM (p = 0.00012) and BRCA2 (p = 0.0025)." (PMID 39749474, 2025). "Such antitumor activity was further validated in PDX and organoids acquired from cancer patients with ATM loss." (PMID 39968096, 2025).
cancer (continued). "A genetic cancer risk assessment in this case revealed her to be a heterozygous carrier of a pathogenic mutation of the ATM gene called c.5763-1050A>G." (PMID 40995169, 2025). "Although the evidence for ATM mutations conferring risks for cancers beyond BC is limited, some studies have suggested potential associations with pancreatic and prostate cancer." (PMID 41049353, 2025). "In this study, the authors showed the ataxia telangiectasia mutated (ATM)/AKT/HIF-1α signaling axis plays a key role in the anti-cancer effects of theasaponin E1." (PMID 41373772, 2025). "This will become more apparent in cases of synthetic lethality where the loss of ARID1A makes cancer cells more susceptible to therapies such as ATM and PARP inhibitors." (PMID 40429787, 2025). "The large size of the ATM gene and the prevalence of variants of uncertain significance have limited the identification of additional cancer associations." (PMID 41331641, 2025). "Multiple research findings suggest that inhibiting ATM or DNA-PK, particularly when combined with radiation or chemotherapy, significantly enhances the susceptibility of cancer cells to these treatments." (PMID 40256842, 2025). "In an analysis of 23 hereditary cancer genes from 3 cohorts, carriers of PV in ATM had a 1.9-fold increased risk of NHL." (PMID 40253392, 2025). "For both the detected variants, the premature stop codons result in the loss of the FAT and the protein kinase domain of ATM, indicating impaired function likely leading to an increased risk of cancer." (PMID 40072281, 2025). "It is thus possible that the benefits of partial pharmacologic ATM inhibition would outweigh any increased risk for cancer." (PMID 40179146, 2025). "Phenotypic variability is also observed in heterozygous carriers of ATM mutations, who face an elevated risk of malignancies, further underscoring ATM’s significance in cancer pathogenesis." (PMID 41451872, 2025). "ATM occupies a distinct position among hereditary cancer susceptibility genes because it represents a medium-penetrance condition, in contrast to high-penetrance syndromes such as LS, HBOC and LFS." (PMID 41331641, 2025). "Loss of ATM function leads to chromosomal instability, radiosensitivity and an elevated cancer risk." (PMID 41065894, 2025). "Investigating VUS, especially in ATM, is essential for understanding cancer predisposition mechanisms, developing targeted therapies and potentially recognizing ATM as BRCA3 due to its functional similarities with BRCA1/2." (PMID 40259910, 2025). "ATM-deficient cancer cells cannot effectively signal DSBs, making them highly dependent on ataxia telangiectasia and Rad3-related protein (ATR) to manage replication stress and DNA damage." (PMID 41190241, 2025). "An earlier detection of the ATM heterozygous variants would have probably allowed further considerations in the therapeutic management of patients and their families about cancer risk assessment." (PMID 39984762, 2025). "This revealed that BRCA1- and ATM-deficient cancer patients with low SETD1A mRNA expression had poorer overall survival outcomes compared to those with higher levels of SETD1A." (PMID 39994444, 2025). "It has been reported that HRD is ubiquitous in a variety of cancers, and ATM and BRCA1/2 have been found to be important mutation drivers." (PMID 39931080, 2025). "Our findings demonstrate that loss of SETD1A also drives PARPi resistance in ATM-deficient cancer cells." (PMID 39994444, 2025). "In a case‒control study consisting of 627,742 patients referred for hereditary cancer testing, the risk of cutaneous MM was also slightly elevated (OR 1.46) in carriers of pathogenic ATM variants." (PMID 41331641, 2025). "An illustrative example is the use of synthetic lethality‐based approaches to exploit weaknesses in DNA repair pathways with PARP inhibitors (olaparib, rucaparib, niraparib, and talazoparib) in cancers harboring BRCA or ATM mutations." (PMID 40636286, 2025).
cancer (continued). "Somatic ATM mutations are also seen across various cancer types and are frequently tested through NGS." (PMID 40622001, 2025). "The findings redefine the therapeutic paradigm beyond DNA damage repair, positioning the ATF4-GDF15 axis as a pivotal biomarker and promising therapeutic target for ATM-deficient cancers." (PMID 41266732, 2025). "ATM gene mutations or low ATM expression in cancer cells lead to reduced cell migration, upregulated autophagy, and enhanced sensitivity to chemotherapy and radiotherapy." (PMID 40554491, 2025). "ATM-deficient cancer cells rely heavily on RAD51-mediated HR because DSB signaling is weakened, and CHK1-deficient cells similarly depend on RAD51 due to impaired checkpoints." (PMID 41190241, 2025). "For BRCA1 and BRCA2 carriers, the finding of a mutation has clear implications for cancer management, but for other genes, such as ATM, the management implications are less clear." (PMID 39543654, 2024). "Depletion of key HR components BRCA2 or ataxia telangiectasia mutated (ATM) in cancer cells conferred up to 12-fold increased sensitivity to the LP-184." (PMID 38630886, 2024). "The cumulative risk of developing any cancer by the age of 80 for ATM PTV carriers was 64% (95% CI 46% to 76%) for females and 69% (61% to 76%) for males, compared with 33% for females and 39% for males in the general population." (PMID 39209703, 2024). "More specifically, ATM has been shown to be mutated in many cancers, including lung, gastric, prostate, and mantle cell lymphomas." (PMID 38807759, 2024). "DNA damage is first recognized by molecular “sensors”, most notably those in the ATR/Chk1- and ATM/Chk2-mediated signalling pathways, which are hyperactivated in various cancers and associated with chemoresistance and poor prognosis." (PMID 38685067, 2024). "Our previous studies conducted on a White population showed a higher cancer risk in ATM + CHEK2 or two CHEK2 PVs than single gene variants." (PMID 39594831, 2024). "In our results, ten patients (1.90%, 10/527) harbored P/LP mutations in the ATM gene, and five (50%, 5/10) carriers had a family history of cancer." (PMID 38350919, 2024). "It is important to note that cancer risks are determined by a combination of multiple factors, including rare gene variants such as those in ATM and CHEK2 studied here, but also lifestyle factors, and commoner genetic variants." (PMID 39209703, 2024). "Synthetic lethality resulting from combining ATM or ATR inhibition with the increased susceptibility of acid-exposed cancer cells to undergo DNA damages positions tumor acidosis as an attractive predictive biomarker for the clinical use of these drugs." (PMID 38366255, 2024). "Although the ATM gene has a significant mutation rate in many human cancers, including colorectal, prostate, lung, and breast, it remains understudied compared with other DDR-involved molecules such as PARP and ATR." (PMID 39033176, 2024). "Our analyses demonstrate that ATM and CHEK2 PTVs are associated with increased risks of a wide range of cancers, with the overall cancer risk being higher for ATM." (PMID 39209703, 2024). "In a recent review, we pointed out that the great majority of cancer syndromes are caused by mutations of genes that encode phosphorylation substrates of ATM, i.e., potential X-proteins." (PMID 38893223, 2024). "In the overall MaBC and FBC cohorts, we compared mutational prevalence in cancer susceptibility genes (CSG) (ATM/BRCA1/BRCA2/CHEK2/PALB2)." (PMID 39049124, 2024). "Heterozygous PVs in ATM are relatively common in the population, with a prevalence of about 0.35%, and they are frequently observed in cancer patients; however, the magnitude of cancer risk remains uncertain." (PMID 38339330, 2024).
cancer (continued). "In conclusion, our study presents evidence that induction of DDR is a hallmark of any cancer cells experiencing an acidic milieu and that ATM and ATR inhibitors can directly take advantage of this context." (PMID 38366255, 2024). "ATM deficiency or ATM inhibition can induce synthetic lethality in cancer cells that harbor other underlying DDR deficiencies." (PMID 38730598, 2024). "Mutations in the ATM gene were shown to sensitize cancer to Pt-derived drugs, on one hand, but also to increased risk of secondary tumors after radiotherapy, on the other hand." (PMID 39268460, 2024). "Patients with ataxia-telangiectasia (A-T) syndrome caused by ATM mutations typically exhibit heightened radiosensitivity and an increased propensity for cancer development." (PMID 39118131, 2024). "For ATM gene, 7 distinct variants in the association of cancer were identified in 7 individuals, from which three were pathogenic/likely pathogenic and four were VUS according to ClinVar and Franklin." (PMID 39148954, 2024). "One reported mechanism of mtDNA leakage in ATM-deficient murine cancer cells is via downregulation of the mitochondrial transcription factor A (TFAM)." (PMID 38084916, 2024). "Two patients exhibited variants in well-known cancer risk genes, ATM c.5558A>T (MPT2) and MLH1 c.1853A>T (MPT11)." (PMID 39408606, 2024). "Cancer associations for coding variants in ATM and CHEK2 were evaluated using whole-exome sequence data from UK Biobank linked to cancer registration data (348 488 participants), and analysed both as a retrospective case-control and a prospective cohort study." (PMID 39209703, 2024). "For ATM rMSVs, there was only a small excess cancer risk overall (RR 1.06 in females and 1.13 in males)." (PMID 39209703, 2024). "Because pathogenic variants in ATM cause both A-T in a biallelic state and cancer predisposition in a heterozygous state, this VCEP was able to leverage evidence from A-T cohorts to inform PVS1 boundaries." (PMID 38854136, 2024). "In the non‐cancer cohort, 25/492 (5%) participants carried 17 unique P/LP variants in ATM, BRCA2, BRIP1, CHEK2, MUTYH, NBN, and PMS2 genes." (PMID 38308423, 2024). "One emerging approach in cancer treatment including HNSCC involves the use of small molecule kinase inhibitors (smKI) targeting Ataxia telangiectasia mutated (ATM) or Ataxia telangiectasia mutated and Rad3-related (ATR) kinases." (PMID 39411143, 2024). "A total of 171 unique patients harboring a germline pathogenic variant in ATM and diagnosed with one of the atypical ATM cancers were identified." (PMID 36865800, 2023). "We then estimated the prevalence of germline ATM pathogenic variants for each relevant cancer type by compiling data from each reviewed study." (PMID 36865800, 2023). "Concomitantly, this mutation is associated with a much smaller cancer predisposition than that associated with ATM or NBS1, suggesting that telomere disruption is the main culprit for the ensuing cancer predisposition." (PMID 37754262, 2023). "The germline pathogenic variants in ATM detected in all six of our patients were discovered through comprehensive hereditary cancer panels." (PMID 36865800, 2023). "PARPi activity was also demonstrated for BRCAwt cancers due to mutations in genes critical for DNA repair (e.g., ATM, BARD1, BRIP1, CHEK2, NBN, PALB2, RAD51C, and RAD51D)." (PMID 36910637, 2023). "RAD50, part of the MREll complex, influences the predisposition to cancer due to its complex interactions with various oncogenes such as ATM, BRCA1, and CHK2." (PMID 38213474, 2023).
cancer (continued). "As a result, it would be difficult to infer the clinical characteristics and implications of loss-of-function mutations of ATM/ATR in cancer patients." (PMID 38041093, 2023). "Ataxia telangiectasia–mutated (ATM serine/threonine kinase) is a further apical kinase of DNA DSB response, that signals in a partially nonredundant fashion with ATR, and ATR inhibitors have synthetic lethal activity in ATM-deficient cancers." (PMID 37773077, 2023). "PARP and ATR inhibitors were tested here because cancer cells with ATM deficiency are sensitive to PARP and ATR inhibition." (PMID 36797243, 2023). "A study reported the effectiveness of AZD6738 in inducing cell death in olaparib-treated ATM-deficient cancer cells while exerting a low effect on ATM-proficient control cells." (PMID 36975494, 2023). "These phenotypes are partially replicated in mouse and zebrafish models with Atm deficiency and the non-cancer related phenotypes in these patients and experimental models have been attributed to functions of ATM that are unrelated to the DDR." (PMID 37190230, 2023). "The findings have important clinical implications by highlighting Gal-9 as a promising therapeutic target for A-T Syndrome and ATM-deficient tumors and revealing combining ATM inhibition with anti-Gal-9 therapy as a novel strategy for cancer treatment." (PMID 36778120, 2023). "ATM gene mutations are commonly associated with increased predisposition to various cancers (more often in hematologic malignancies) and poor prognosis because ATM has a crucial role in the repair of DNA double-strand breaks." (PMID 37892022, 2023). "Nevertheless, these germline ATM pathogenic variants were associated with a significant proportion of the known causes for hereditary cancer susceptibility in these cancers." (PMID 36865800, 2023). "Coherently with this idea, patients suffering from ATLD, NBS, and NBSLD are typically characterized by a decrease in ATM activation or activity, genome instability, and cancer predisposition." (PMID 37509263, 2023). "A comprehensive review of the literature found 25 relevant studies where 171 individuals with a germline deleterious ATM variant have been diagnosed with the same or similar cancers." (PMID 36865800, 2023). "In some cases, trials are taking advantage of ATM mutations that occur frequently across cancers and are synthetically lethal with ATR or DNA-PKcs deficiency." (PMID 38201511, 2023). "There is limited understanding of radiation-associated toxicities across various cancer disease sites, normal uninvolved organ tissues, and radiation treatment modalities in patients with heterozygous germline ATM variants." (PMID 37206490, 2023). "The ATM protein has roles in double‐stranded DNA repair and thus ATM variants lead to genomic instability with increased sensitivity to ionising radiation and elevated cancer risk (22%–24% cumulative incidence up to age 20 years)." (PMID 37264737, 2023). "Nevertheless, our review of the literature indicates that the prevalence of germline ATM pathogenic variants among individuals diagnosed with these atypical cancers appears to be less than 1% in most cases." (PMID 36865800, 2023). "The ATM pathway also regulates the suppression of anti-tumor immune cancer-associated fibroblasts (CAFs) differentiation." (PMID 37033966, 2023). "Meanwhile, none of the pathogenic germline ATM variants identified in our six patients overlapped among the somatic loss-of-function ATM variants present in the cancer sequencing datasets." (PMID 36865800, 2023). "Because interferon signaling plays a crucial role in modulating cancer immunotherapy, we next aimed to identify the ISGs that were upregulated by ATM inhibition and implicated in ICB therapy." (PMID 37174688, 2023). "The personal and family history of cancer among the six patients with malignancies atypical for ATM-associated hereditary cancer susceptibility were then evaluated in detail." (PMID 36865800, 2023).